MCM2 (minichromosome maintenance complex component 2)
Diseases named in the same sentence as MCM2 in open-access papers (continued):
Sharing a sentence is not in itself a finding about the gene and the disease.
cancer (continued). "Malignancies often exhibit defective minichromosome maintenance protein 2 (MCM2), a cancer proliferation biomarker that serves as a licensing factor in the initiation of DNA replication." (PMID 29038488, 2017). "In this study, the expression levels of CDC20, BUB1, MCM2, and cyclin B1 were upregulated in the 3 and 10 μmol/l genistein groups, indicating the promoting effects of genistein on cancer cell proliferation." (PMID 25385471, 2015). "The KEGG pathway analysis results indicated that among 26 genes some of them were found to have roles in cancer related pathways like cell cycle (MCM2), Jak-STAT (SOCS1), MAPK (STMN1), PPAR signaling pathways (ME1)." (PMID 25978727, 2015). "CD133 and ALDH-1 were expressed more frequently in the TNBC group, which expressed high levels of MCM2, than in the other cancer subtypes." (PMID 26430873, 2015). "This difference suggests that MCM2 is a more sensitive proliferation marker in malignant neoplasms than is Ki-67." (PMID 26823641, 2015). "In conclusion, our data suggest that cancer therapy using Hph-1-gp70 and doxorubicin is effective for treating cancers with high MCM2 expression, including CSCs." (PMID 26430873, 2015). "KPNA2, a gene overexpressed in many cancers, and MCM2 gene, an initiator of replication and necessary for entry into S phase of the cell cycle, were downregulated in the human cell cycle array." (PMID 24147107, 2013). "These combined data are suggestive of a potential gradient of susceptibility, but that there is a critical minimum threshold of MCM levels, between ∼35 and 50% in the case of MCM2, required to avoid early cancer and other developmental defects." (PMID 20838603, 2010). "In benign biliary strictures, Mcm2 and -5 protein expression was confined to the basal epithelial proliferative compartment – in contrast to malignant strictures where expression was seen in all tissue layers." (PMID 18414413, 2008). "In carcinomas, a statistically significant inverse relation was observed between MCM-2 and p27Kip1 levels (Spearman's rho=−0.3277, P=0.0068)." (PMID 17940502, 2007). "MCM2, a cell cycle regulatory protein, is highly expressed in cervical and other cancers." (PMID 40507244, 2025). "MCM2, involved in DNA replication, is a key marker for various cancers." (PMID 39508903, 2024). "MCM2 was significantly upregulated in almost all cancers and cancer subtypes in The Cancer Genome Atlas and was correlated with the progression and poor prognosis of malignant tumors." (PMID 36769104, 2023). "The risk stratification machine learning model using Logistic regression (L1 regularization) combining morphological parameters and molecular markers-αvβ6, EGFR, CD17, McM2, geminin, and Ki-67 differentiated cancer and HGD from LRL with sensitivity and specificity of 78% and 88% respectively." (PMID 37747904, 2023). "MCM2 plays an important role in the pathological process of cancers, but the effect of MCM2 in microvascular endothelial cells under hypoxia remains unclear." (PMID 36769104, 2023). "Recent studies have shown that MCM2 is significantly upregulated in 30 cancers and may be a potential marker for various cancers." (PMID 36769104, 2023). "However, MCM2 expression positively correlated with all six immune cell infiltrates in only four cancers (HNSC, LGG, LIHC, PRAD)." (PMID 35693940, 2022). "A previous transcriptome analysis suggested MCM2 as a pan-cancer biomarker." (PMID 35906577, 2022). "Consistent with our pan-cancer analysis findings that MCM2 is a potential biomarker for cancer diagnosis and prognosis, our results also indicated that MCM2 is an independent prognostic gene for SKCM, as assessed by a nomogram model according to baseline clinical data." (PMID 35693940, 2022). "Minichromosome maintenance 2 (MCM2) is a member of the minichromosomal maintenance family of proteins that mainly regulates DNA replication and the cell cycle and is involved in regulating cancer cell proliferation in various cancers." (PMID 35693940, 2022).
cancer (continued). "In addition to MCM2 to MCM7, six downstream oncogenic targets of c-MYC implicated in cancer survival and metabolism including PSMA1, PSMA6, PSMB2, HDAC2, LDHA and SPRING were positively correlated with IFITM3 in 71 GC specimens using the Cho dataset." (PMID 35941699, 2022). "Then, the prognostic value of MCM2 expression in patients with various cancers was analyzed." (PMID 35693940, 2022). "In the TCGA cohort, higher TMB was correlated with different types of MCM2 mutations across cancers, which were significantly different among cancers with no mutation, truncating mutants, missense mutants or multiple mutations." (PMID 35693940, 2022). "First, the correlation between the transcription levels of MCM2 and cancer stage was analyzed." (PMID 35693940, 2022). "Other cancers had a weak correlation between MCM2 expression and 1 or 2 ICGs." (PMID 35693940, 2022). "Some previous studies have been reported on MCM2 in different cancers." (PMID 35693940, 2022). "However, the overexpression of MCM2 was found in a number of cancer types, positively related to the progression of cancer, and even served as a sensitive biomarker for diagnosis, prognosis, and response prediction." (PMID 36303105, 2022). "However, according to previous studies, MCM2 plays an role in promoting cancer development in different cancer subtypes." (PMID 35693940, 2022). "A recent article showed that MCMBP accumulates at high levels in cancer cells, which may be related to the overexpression of MCM2–7 observed in many cancerous tissues." (PMID 35438632, 2022). "In summary, MCM2 has the potential to promote cancer progression." (PMID 36303105, 2022). "Our results suggested that MCM2 has a good ability to predict patient OS across cancers." (PMID 35693940, 2022). "Recently, MCM2 has been reported to be overexpressed in various cancer tissues." (PMID 35693940, 2022). "In summary, the results of the multivariate analysis provide a systematic and comprehensive review of the biological characteristics of MCM2 across cancers and revealed that MCM2 might be a promising biomarker for cancer diagnosis and prognosis." (PMID 35693940, 2022). "Moreover, the expression of MCM2 in cancer tissue was significantly increased in 65 datasets and decreased in two datasets." (PMID 34178669, 2021). "Among the MCM family, MCM2 is the most investigated in cancers." (PMID 34859821, 2021). "Moreover, we overlapped the results from this REC analysis with the relationships between basal cell-line expression of MCM2 or MCM10 to drug sensitivity data obtained from the Cancer Therapeutics Response Portal (CTRP) data set." (PMID 35056094, 2021). "Ki-67 has been widely used as a conventional marker for cell proliferation; thus, MCM-2 may have the same potential as Ki-67 for cancer progression evaluation." (PMID 34272446, 2021). "Furthermore, the level of MCM2 in cancer tissues was increased in 65 datasets and decreased in 2 datasets compared to normal tissues." (PMID 32964028, 2020). "In particular, MCM2 was reported by different studies to be a possible cancer marker." (PMID 33153038, 2020). "MCM2 is activated in response to growth signaling pathways and stimulates DNA replication, and therefore highly expressed in active proliferative cells, including cancer cells." (PMID 32469983, 2020). "Moreover the Mcm2 luminal to basal cell ratios were significantly higher in the normal glands from prostates with cancer than in the normal glands from prostates free of cancer." (PMID 32860339, 2020). "In our study, after screening a group of biomarkers which may have potential field effects, we found that the immunoreactivity of p‐STAT3, Mcm2 + and/or MSR1 were associated with cancer and HGPCa at repeat biopsy." (PMID 32860339, 2020). "Diagnostic accuracy analysis of these DEGs in TCGA datasets COAD and LUAD showed that a gene panel that consists of CALU, AURKA, and MCM2 could successfully distinguish cancer tumors from healthy samples." (PMID 32469983, 2020).
cancer (continued). "Additionally, comparison of CALU, AURKA, and MCM2 proteins between healthy samples, early and advanced tumors showed that the level of these proteins was increased through normal–carcinoma transition in both types of cancers." (PMID 32469983, 2020). "MCM2 has also been applied as a proliferation marker in many types of cancer." (PMID 31143171, 2019). "Mcm2 is extensively studied as a prognostic marker for cancer." (PMID 29651420, 2018). "Evidence has shown that Cdc7-selective inhibitors may decrease MCM2 phosphorylation, inhibit DNA synthesis, and cancer cell viability." (PMID 30062004, 2018). "MCM2 can serve as a cell proliferation marker to differentiate normal and cancer cells." (PMID 28008150, 2017). "Our investigation revealed the downstream events of phosphorylation that affect cancer cell proliferation, such as MCM2 promoting cell proliferation might possibly via the regulation of HMGA1 phosphorylation." (PMID 29038488, 2017). "Furthermore, poor patient survival corresponds with increased expression of MCM2 in prostate, lung and breast cancer cells." (PMID 27780919, 2016). "And they could be regarded as indicators for certain cancer progression and prognosis.Our results also suggested that some members of MCM2-7 complex could predict PC progression (MCM4 for T stage)." (PMID 27695057, 2016). "Although several problems must be solved with regard to its application in humans, cancer therapy that exploits the apoptosis-enhancing effect of MCM2 might offer a cure for various cancers." (PMID 26430873, 2015). "Mcm2 may therefore be a biomarker of cells with replication potential (licensed to cycle), and suggestions on potential as a pre-cancer marker have been made." (PMID 23618321, 2013). "Furthermore, we have identified additional genes downregulated by Cl-amidine, including MKI67, MCM5, and MCM2, each with known functions in cancer progression." (PMID 23110523, 2012). "Further genetic reductions of Mcm2, 6, or 7 in this background caused various phenotypes including synthetic lethality, growth retardation, decreased cellular proliferation, GIN, and early onset cancer." (PMID 20838603, 2010). "We have previously reported that the replication licensing pathway is deregulated early in epithelial carcinogenesis, and that the increased growth fraction detected by Mcm2–7 antibodies compared to Ki67 antibodies can be exploited for cancer detection and surveillance." (PMID 16278669, 2005). "The results suggest that while ORC may be essential to load MCM2–7 in many physiological conditions, during development, and even in current in vitro MCM2–7 loading reactions, the mammalian cancer cell is capable of loading functional and excess MCM2–7 in the absence of the six-subunit ORC." (PMID 40530691, 2025). "Therefore, higher levels of MCM2 predicted worse OS across cancers." (PMID 35693940, 2022). "Additionally, MCM2 is high accurate in diagnosing various cancers." (PMID 35693940, 2022). "Similarly, the MSI MANTIS score was higher in cancers with multiple MCM2 mutations (0.32; 0.30–0.74) than no MCM2 mutations (0.30; 0.29–0.33, p < 0.05)." (PMID 35693940, 2022). "Additionally, we analyzed the sensitivity of MCM2 to anticancer drugs in various cancers by using genomics of drug sensitivity, which indicated that MCM2 could serve as potential biomarkers for drug screening and affect clinical responses to treatment." (PMID 35693940, 2022). "Moreover, mice expressing a reduced level of MCM2–7 are prone to developing cancers." (PMID 35438632, 2022). "Moreover, we found that MCM2 expression is strongly related with immune cell infiltration and immune-related molecule expression in most cancers, indicating that MCM2 may be a promising biomarker for immune therapy." (PMID 35693940, 2022).
cancer (continued). "We determined whether there were any changes in the phosphorylation level of MCM2 across cancers." (PMID 35693940, 2022). "Furthermore, CHEK1, BUB1B, and MCM2 could promote cancer cell proliferation, and which were enriched in cell cycle pathways in GSEA analysis for CCA." (PMID 33221765, 2020). "Transcriptomic analysis revealed the upregulation of cell cycle- (MKI67, CCNE2 etc.)and cancer-related genes (SYK, MCM2 etc.), and GSEA confirmed the enrichment of Rb-related pathways." (PMID 41535675, 2026). "Most cancer cell lines (>90%) are unaffected by MAP3K7 depletion, assessed by a DepMap gene dependency score above −0.5, in contrast to common essential gene MCM2." (PMID 38632238, 2024). "Therefore, MCM2 may represent a crucial target for cancer therapeutics." (PMID 38454443, 2024). "MCM2 belongs to MCM family and participate in the regulation of cell proliferation and the development of cancers." (PMID 38466483, 2024). "The genes in Cluster-1, such as MCM2, STAT1, BRCA1, and MCM5, are overexpressed in the cancer samples." (PMID 37925498, 2023). "Next, univariate logistic regression analysis based on data from TCGA further determined the relationship between MCM2 expression in SKCM and clinicopathological variables, including cancer stage (T, N, M, or pathological stage), sex and age." (PMID 35693940, 2022). "Immunohistochemistry confirmed that cancer stem cell markers, such as ALDH-1 and CD133, were frequently expressed and colocalized with MCM2." (PMID 36303105, 2022). "However, the clinical value of MCM2 proteins across cancers remains unclear." (PMID 35693940, 2022). "In conclusion, MCM2 plays a pivotal role in immunotherapy of the TME, prognoses and therapeutic response across all TCGA cancers by affecting infiltration of immune cells." (PMID 35693940, 2022). "MCM2 is a proliferative marker and positively correlates with TNM stage and lymph node metastasis in many cancers." (PMID 36303105, 2022). "The difference in MCM2 expression between the HCC and liver tissues can be used to effectively distinguish cancer tissue from paraneoplastic cancer tissue." (PMID 36243809, 2022). "IHC staining of HCC tissue samples showed that MCM2 and NUP37 were mainly expressed in nucleoplasm of carcinoma cells." (PMID 35093119, 2022). "Using western blotting assays, we quantitatively analyzed MCM2 expression in HCC and para-carcinoma tissues of 16 patients at the First Affiliated Hospital of Guangxi Medical University." (PMID 36243809, 2022). "Well-known biological markers of cell proliferation, including MCM-2 and Ki-67, along with the proto-oncogene, EGFR, have been reported to play pivotal roles in the pathogenesis of several cancers, including LSCC2,3." (PMID 34272446, 2021). "We observe that the mini-chromosome maintenance proteins (MCMs) MCM2, MCM3, MCM6 and MCM7, which were upregulated in most of the cancers, also regulate the expression of a significant number of high centrality genes in the network." (PMID 34728699, 2021). "Based on high-throughput screening of 2 million compounds, AS4583 was found to inhibit the cell proliferation and DNA replication of cancer cells via the disruption of the MCM complex, especially MCM2." (PMID 33801812, 2021). "The results showed that MCM2 is upregulated in human EC and is related to worse OS and PFS, which is consistent with reports of other cancers." (PMID 34859821, 2021). "We demonstrate that cyclin E2 localises with core preRC (pre-replication complex) proteins (MCM2, MCM7) on the chromatin of cancer cells." (PMID 32823571, 2020). "e is natural logarithm and when predicting cancers, P = p‐STAT3 × 0.009138 + MSR1 × −0.005494 + Mcm2 × 0.133981 + (−0.654652)." (PMID 32860339, 2020). "To examine the link between MELK and cell division in cancer, we compared the levels of MELK expression with five well-characterized proliferation markers: MKI67, PCNA, CCNB1, MCM2, and TOP2A." (PMID 29417930, 2018).
cancer (continued). "As a result, we confirmed DNA polymerization complex genes, such as MCM2, PCNA, and cell cycle related genes, that were depleted by metformin treatment in RNA and protein level in 5-Fu resistant cancer cell line." (PMID 28915611, 2017). "To validate our findings, we conducted a study of the literature by randomly selecting five genes (DBF4, MCM2, ID3, EXOSC4, and CDKN3) from the 565 potential cancer genes." (PMID 25866773, 2015). "Through knocking down of MCM2 by siRNA, studies demonstrated that the MCM2 expression impaired the growth of the prostatic (LNCaP) and colon (HCT116) cancer cell lines." (PMID 25098679, 2014). "We selected the overlapped genes-PLK1, MCM2, MCM3, MCM7, MCM10 (ranked 13 by NGP-NR in NSCLC patient datasets) and SKP2 to investigate their functions in cancer." (PMID 22838965, 2012). "The subsequent finding that mice (Mcm2IRES-CreERT) containing ∼1/3 the normal level of MCM2 had GIN and and cancer lent support for the idea that reductions in MCMs contribute to the Chaos3 phenotypes." (PMID 20838603, 2010). "Comparison of the mouse skin pRb/p107/p130 signature mapped to human genes with Signature 5 of mucosal HPV-carcinomas revealed a significant overlap of 7 genes: DHFR, E2F1, LIG1, MCM2, PCNA, RFC4, TYMS and USP1." (PMID 19721808, 2009). "The most dramatic and uniform changes we observed were in a set of about 30 genes that are characterized as a "cancer proliferation cluster," which includes genes expressed during mitosis (CDC2, CDC25, MCM2, PLK1) and following DNA damage." (PMID 17233903, 2007). "Both Ki-67 and Mcm-2 showed an upward trend from normal tissue through HGPIN and cancer with a shift in proliferation from basal to luminal compartment." (PMID 16545117, 2006). "This study quantified and validated four cervical precancer and cancer biomarkers—TOP2A, MCM2, VCP, and p16INK4a—in lysates of cultured HeLa, Ca Ski, HT-3, and C-33 A cancer cell lines, as well as normal PCS cells, clinical cervical swab specimens, and cervical tissues." (PMID 40507244, 2025). "Additionally, the expression of MCM2, PNCA, and E2F4 genes was reduced in COLO-205 cancer cell lines." (PMID 40872562, 2025). "The literature has demonstrated overexpression of MCM2, MCM4, and MCM6 in various cancers." (PMID 40445576, 2025). "Based on the cancer panel, we uncovered that there was up‐regulation in several markers, including GADD45 and CASP9, whilst there was down‐regulation in markers like APAF‐1 and MCM2." (PMID 38938916, 2023). "MT, E-Cadherin and MCM2 staining significantly differentiated between non-malignant and all groups of malignant tumors." (PMID 36676734, 2023). "Patients with MCM2 mutant cancers had higher MSIsensor scores (3.26; 0.045–17.17) than those with MCM2 nonmutant cancers (0.05, 0–0.31; p < 0.05)." (PMID 35693940, 2022). "In general, TMB was higher in patients with MCM2 mutant cancers (median: 21.23; interquartile range: 9.72–86.23) than MCM2 nonmutant cancers (0.63, 0.87–4.37; p < 0.05)." (PMID 35693940, 2022). "The correlation was evaluated between MCM2 expression and the infiltration of six immune cell types (B cells, CD4+ T cells, CD8+ T cells, dendritic cells, macrophages and neutrophils) and the purity in 32 TCGA cancers and subtypes." (PMID 35693940, 2022). "The differential expression of MCM2 has been reported in many cancers, but a comprehensive pan-cancer analysis is lacking." (PMID 35693940, 2022).